MSH6 (mutS homolog 6)
Diseases named in the same sentence as MSH6 in open-access papers (continued):
Sharing a sentence is not in itself a finding about the gene and the disease.
colorectal cancer (continued). "It has been reported that MSH6 mutations could increase the incidence of glioma, and the mutation frequency of MSH6 was 7.2% in colorectal cancer and 9.6% in endometrial cancer." (PMID 38200495, 2024). "Similarly, extensive loss of MSH6 expression (18%) was found common among colorectal carcinomas treated with neoadjuvant radiotherapy despite preserved pre-treatment staining and stable microsatellite." (PMID 35718836, 2023). "MSH6 is one of the DNA mismatch-repair genes that play a significant role in repairing mis-incorporated bases and DNA damage, and it is reported that frameshift variants in MSH6 are observed in colorectal cancer at a particular frequency." (PMID 35228610, 2022). "If colorectal cancer was diagnosed before the age of 25 years in the family, then this should be started 2–5 years earlier than this age, but for MSH6 variants, starting at the age of 30 years or 10 years earlier than the youngest age of onset in the family should be considered." (PMID 34185173, 2021). "The mutation of MSH6, for example, may increase the risk of developing colorectal carcinomas, and MYO16 appears to have an important role in neural development and the function of the nervous system." (PMID 33451291, 2021). "We describe a family severely affected by colorectal cancer (CRC) where whole‐exome sequencing identified the coinheritance of the germline variants encoding MSH6 p.Thr1100Met and MUTYH p.Tyr179Cys in, at least, three CRC patients diagnosed before 60 years of age." (PMID 32615015, 2020). "In the UK10K cohort, 4 individuals had truncating mutations in MSH6 (0.29%, approximately 1:350), which would cause an increase in colorectal cancer risk (by 8 times) and in endometrial cancer risk (26 times) more than the general population in these individuals." (PMID 29641532, 2018). "Although germline mutations of MSH6 gene in early onset colorectal cancer have been reported, this difference in age of onset and associated risk may explain why MSH6 mutations constitute a minor fraction of cases." (PMID 26557847, 2015). "In fact, overexpression of a truncated form of MBD4 lacking the glycosylase domain in a BigBlue-transfected human MSH6-deficient colorectal cancer cell line, led to a 2-fold increase in mutation frequency and predisposed to chromosomal instability, compared to controls." (PMID 26503472, 2015). "Moreover, mutations in the MSH6 gene have also been linked to a lower risk of colorectal cancer and a higher risk of endometrial carcinoma." (PMID 26557847, 2015). "Finally, we examined six cases from patients who underwent surgery for colorectal cancer at Saint-Antoine Hospital and whose tumours showed loss of MSH6 expression alone." (PMID 21081928, 2010). "To evaluate the contribution of germline MSH6 mutations to early-onset colorectal cancer, we have analysed peripheral blood of 38 patients diagnosed with this disease before 45 years of age and who presented no family history of hereditary nonpolyposis colorectal cancer-related cancers." (PMID 16940983, 2006).
colorectal cancer (continued). "For example, MSI testing may both be less specific in older patients (where somatic MLH1 hypermethylation is known to be more common in colorectal cancer) and may be less sensitive to identify path_MSH6 and path_PMS2 cases (i.e., pathogenic variants in MSH6 and PMS2)." (PMID 32492863, 2020). "As the Amsterdam II criteria have a reported sensitivity of 60-80% for colorectal cancer, but of only 20-30% in consecutive endometrial cancers, it is likely that our selection criteria have missed a number of LS families, especially those caused by MSH6 mutations." (PMID 24851142, 2014). "Microsatellite instability (MSI) is a key feature in colorectal carcinomas (CRCs), but its role in diagnosis and prognosis, particularly through immunohistochemical markers like MSH6 and PMS2, remains underexplored." (PMID 41907888, 2025). "In the two MSH6 cases, the discrepancy between the families can potentially be explained by the variable but generally low penetrance of MSH6 in colorectal cancer." (PMID 39516274, 2024). "Among previously not reported associations with overall survival were mutations in GATA3 and FANCE genes in colorectal cancer, mutations in gene PTPN11 in glioma, and mutations in RNF43, MSH6 and FBXW7 genes in endometrial cancer." (PMID 39277826, 2024). "Mismatch repair-deficient colorectal cancer clones adapt their mutation landscape by toggling homopolymer sequences in MutS homolog 3 (MSH3) and MutS homolog 6 (MSH6)." (PMID 38956208, 2024). "According to our study, MSH6 gene is associated with tumor stage and immunotherapy response in patients with MSI‐H colorectal cancer." (PMID 38746969, 2024).
colorectal cancer (continued). "Some colorectal cancers are signified by MMR deficiencies, such as LOF of MSH3 or MSH6, creating a high number of deletions in repetitive DNA." (PMID 36883553, 2023). "Comparing the results of the present study and our previous study in colorectal cancer, we observed that MSH6 and EXO1 genetic mutations were higher in EMAST+/MSI-H tumors than other subtypes, in both GC and colorectal cancer." (PMID 32120855, 2020). "Our previous study regarding mutations in DNA-repair-associated genes in colorectal cancer demonstrated that EMAST+/MSI-H tumors had a higher frequency of MLH1, MSH3, MSH6, PMS2, and EXO1 genetic mutations than the other three colorectal cancer subtypes." (PMID 32120855, 2020). "The three pathogenic variants included two colorectal cancers with MLH1 loss and high MSI and one endometrial cancer with MSH6 loss and microsatellite stability." (PMID 31386297, 2019). "This revision emphasized MSH6, which as also been observed mutted in hypermutated tumors in gliomas, prostate, and colorectal cancers." (PMID 31294536, 2019). "MSH6 is a mismatch repair gene involved in colorectal cancers, and it was reported that most patients with colorectal cancer carrying an MSH6 mutation were diagnosed after the age of 50 and had distally localized tumors." (PMID 31116002, 2019). "The simultaneous occurrence of the G/A genotype of the MSH6 gene and the C/C genotype of the PMS2 gene was found to increase the risk of colorectal cancer (OR = 1.78 95% Cl: 1.07–2,98 p = 0.029)." (PMID 28451866, 2018).
colorectal cancer (continued). "We further validated several new targets (histone H3F3B and MSH6) of miR-215 based on their potential biological significance in colorectal cancer." (PMID 26287603, 2015). "Detection of MSI in cancers with MSH6 mutations can be problematic as they often exhibit an attenuated MSI phenotype, as well as reduced penetrance of colorectal cancer and a later age of onset." (PMID 26252492, 2015). "The aim of this report is to present a unique case of early‐onset colorectal cancer characterized by the rare co‐occurrence of a germline MSH6 PVs and constitutional MLH1 promoter hypermethylation, highlighting the implications of digenic mechanisms in LS diagnostics and management." (PMID 41347766, 2026). "This includes pathogenic variants in MSH6, which is associated with colorectal cancer but not with polyposis." (PMID 39516274, 2024). "Therefore, the response mechanism of the MSH6 gene to immune therapy in MSI‐H colorectal cancer patients requires further exploration." (PMID 38746969, 2024). "Similarly, loss of MMR genes such as MLH-1, PMS-2, MSH-2 and MSH-6 leads to MSI and increases the risk of colorectal cancers (CRC)." (PMID 38134458, 2023).
colorectal cancer (continued). "As one of the three most important mismatch repair genes in the MutS family, MSH6 has been shown to be involved in the occurrence and development of many different cancers, including colorectal cancer, endometrial cancer, prostate cancer, pituitary adenoma and osteosarcoma." (PMID 34941572, 2021). "We first compared chiral microsatellite sequins to tumor samples from nonpolyposis colorectal cancer patients with confirmed DNA mismatch repair deficiency (due to mutations in MSH6 or MLH1) via PCR and gel electrophoresis." (PMID 30902988, 2019). "The purpose of the study was to evaluate the association between gene polymorphisms Glu39Gly (c.116G > A) of MSH6 gene and IVS1-1121C > T of PMS2 gene and sporadic colorectal cancer risk, in a case-control study comprising 200 patients and 200 controls origination from polish population." (PMID 28451866, 2018). "Four of 48 SAPs in MSH6 (OMIM:600678) are FN with “colorectal cancer” HGMD annotations." (PMID 27468419, 2016). "We also selected some important targets that may play key roles in colorectal cancer for validation namely, MSH6 and histone H3F3B." (PMID 26287603, 2015). "Mutations in both MSH6 and PMS2 genes have been suggested to affect families with atypical LS, which presents with a late onset of disease, lower incidence of colorectal cancer and a high incidence of endometrial cancer; the latter is noted for MSH6 mutations only." (PMID 26437257, 2015). "In colorectal cancer, mutations have been found in a number of genes with key cellular roles, such as growth factor receptors (TGFBR2 and IGF2R), genes involved in apoptosis (BAX), as well as genes relevant for DNA repair (MSH3, MSH6)." (PMID 20979647, 2010). "Furthermore, the mutational frequency in MSI-H colorectal cancer is 20 to 39% for MSH3 and 30 to 40% for MSH6." (PMID 20979647, 2010). "Furthermore, studies have demonstrated that MSH6 mutations account for 10–15% of all MMR gene mutation in LS-associated EC, and patients with MSH6 mutations exhibit a higher risk of developing EC than colorectal cancer (CRC)." (PMID 41154599, 2025). "It has been reported that, in patients with colorectal cancer receiving preoperative chemoradiotherapy, the tumor MSH6 expression may be lost even in the absence of MSH6 variants." (PMID 34185173, 2021). "In addition, loss of MSH6 promotes tumorigenesis in colorectal cancer is well known, but not in ovarian cancer." (PMID 26436112, 2015).